KIFC1 (kinesin family member C1)
Diseases named in the same sentence as KIFC1 in open-access papers (continued):
Sharing a sentence is not in itself a finding about the gene and the disease.
gastric cancer (9 papers, 2018 to 2025). A primary or metastatic malignant neoplasm involving the stomach. "High KIFC1 expression in gastric cancer promotes proliferation, migration, and invasion of gastric cancer cells." (PMID 40612867, 2025). "For instance, miR-135a-5p promoted the progression of head and neck squamous cell carcinoma by targeting HOXA10, the progression of thyroid carcinoma by VCAN, and the progression of gastric cancer by KIFC1." (PMID 32010197, 2019).
lung carcinoma (9 papers, 2015 to 2025). "Collectively, these results established KIFC1 as a valuable prognostic and diagnostic indicator for lung cancer." (PMID 38457554, 2024). "To establish the diagnostic value of KIFC1 in lung cancer, we assessed the relationship between KIFC1 expression and the clinical phenotype." (PMID 38457554, 2024). "Survival analysis revealed that increased KIFC1 expression was associated with poor overall survival, first-progression survival and post-progression survival in lung cancer." (PMID 38457554, 2024). "In terms of aggressiveness, previous studies have indicated an association between KIFC1 expression and brain metastasis in primary NSCLC However, the molecular mechanisms underlying the role of KIFC1 in lung cancer remain unclear." (PMID 38457554, 2024). "Given the association between KIFC1 and brain metastases in lung cancer, we also hypothesized that KIFC1 is critical for TNBC cell migration." (PMID 28218233, 2017). "Thus, this study aims to find out the association between KIFC1 and lung cancer." (PMID 38457554, 2024). "Survival analysis revealed that overexpression of CDK1, PLK1, AURKA, KIFC1, and KIF2C was associated with a statistically significant unfavorable overall survival in patients with lung cancer." (PMID 40232858, 2025). "In conclusion, this study primarily used bioinformatics analysis and functional investigations to demonstrate that KIFC1 served as a biomarker and therapeutic target in lung cancer." (PMID 38457554, 2024). "Compared to normal lung tissues, both mRNA and protein levels of KIFC1 were significantly increased in lung cancer tissues." (PMID 38457554, 2024). "Our findings provide compelling evidence that KIFC1 served as a novel biomarker for the malignant progression of lung cancer, which highlighted its potential relevance in LUAD progression." (PMID 38457554, 2024). "Results revealed a significant inhibition of invasion in H1299 lung cancer cells with 300 nM AZ82, suggesting that the suppression of KIFC1 is advantageous in impeding the development of lung cancer." (PMID 38457554, 2024). "Consistently, immunohistochemistry (IHC) results obtained from the HPA database also demonstrated high expression of KIFC1 in lung cancer." (PMID 38457554, 2024). "A previous study showed that KIFC1 was overexpressed in lung cancer tissues, and the high KIFC1 mRNA expression subgroup had worse overall survival and progression-free survival." (PMID 39349439, 2024). "In this study, we conducted a comprehensive analysis of KIFC1 expression in lung cancer patients using bioinformatics tools and fresh tissue samples." (PMID 38457554, 2024). "The protein and mRNA expression levels of KIFC1 in lung cancer tissues were significantly higher than those in para-carcinoma tissues, which was consistent with the results of the bioinformatics analysis." (PMID 38457554, 2024). "To delve deeper into the importance of KIFC1 in lung cancer, we conducted inhibition experiments using the KIFC1 small molecule inhibitor AZ82." (PMID 38457554, 2024). "By analyzing the differentially expressed genes in animal models and human tissue cohorts, several genes, including CDH2, KIFC1, and FALZ, were identified to be highly associated with lung cancer brain metastasis." (PMID 26883469, 2016). "Based on real-world cohort results, western blotting and RT-qPCR showed high-KIFC1 expression in lung cancer, which may be related to the malignancy of lung cancer." (PMID 38457554, 2024). "Therefore, our analysis revealed that both the mRNA and protein expression levels of KIFC1 were significantly upregulated in lung cancer." (PMID 38457554, 2024). "Using flow cytometry to examine the cell cycle, we found that silencing KIFC1 could arrest the cell cycle in G2/M phase, suggesting that KIFC1 can be used as a biomarker for lung cancer diagnosis and treatment." (PMID 32391047, 2020).
lung carcinoma (continued). "Functionally, KIFC1 depletion is associated with various anti-cancer effects, including suppressed proliferation, colony formation, cell growth, invasion, and migration, while its overexpression enhanced malignant phenotypes in H1299, PC9, A549, and SPC-A1 lung cancer cells." (PMID 40002279, 2025). "In lung cancer, both RNA and protein expression of KIFC1 is elevated in LUAD, LUSC, and SCLC tumours compared to healthy lung tissues, which may be attributable to loss of regulatory DNA methylation (i.e., hypomethylation) at the KIFC1 genomic locus." (PMID 40002279, 2025). "However, the precise role of KIFC1 in lung cancer remains to be elucidated." (PMID 38457554, 2024). "Finally, we demonstrated our analysis through in vitro experiments, and the results showed that KIFC1 inhibitor could significantly inhibit the proliferation and invasion of lung cancer cells, indicating that KIFC1 had the potential as a therapeutic target." (PMID 38457554, 2024). "Therefore, we analyzed the expression of KIFC1 in lung cancer cells." (PMID 38457554, 2024). "Finally, experiments in vitro showed that KIFC1 inhibitor could significantly inhibit the proliferation and invasion of lung cancer cells." (PMID 38457554, 2024). "The analysis revealed that KIFC1 expression was significantly higher in lung cancer tissues than in adjacent non-tumor tissues (GSE7503) and healthy individuals (GSE116959 and TCGA; P < .001)." (PMID 38457554, 2024). "To establish the relationship between KIFC1 and lung cancer, we evaluated the expression levels of KIFC1 in lung cancer and non-tumor tissues using data from TCGA and GEO databases (GSE116959 and GSE7503)." (PMID 38457554, 2024). "KIFC1 was identified as a component gene in an expression signature predictive of NSCLC metastasis to the brain, and its expression was elevated in the serum of lung cancer patients compared to healthy individuals, indicating its potential utility as a prognostic biomarker." (PMID 40002279, 2025). "Although, we found that inhibition of KIFC1 inhibits cell proliferation of LUAD, we could not establish the underlying mechanisms of KIFC1 in lung cancer, which needs to be verified." (PMID 38457554, 2024).
triple-negative breast carcinoma (9 papers, 2017 to 2025). An invasive breast carcinoma which is negative for expression of estrogen receptor (ER), progesterone receptor (PR), and human epidermal growth factor receptor 2 (HER2). "Additionally, KIFC1 has been associated with aggressive breast tumor molecular subtypes, such as basal-like and triple-negative breast cancers." (PMID 34945833, 2021). "In parallel siRNA screens of deubiquitinase enzymes, we identify OTUD6B as a positive regulator of KIFC1 expression that is required for centrosome clustering in triple-negative breast cancer (TNBC) cells." (PMID 39789388, 2025). "Recently, using an integrated genomic and siRNA functional validation approach, KIFC1 was independently identified as a malignant cell-specific dependency factor in triple-negative breast cancers." (PMID 31506331, 2019). "KIFC1 is reported to be essential in metastasis of both NSCL as well as triple-negative breast cancer." (PMID 28977870, 2017). "KIFC1 is also observed to be linked with metastasis in NSCL (non-small cell lung cancer) and triple-negative breast cancer." (PMID 28977870, 2017). "In addition, it is consistent with a previous study that high expression of KIFC1 in the nucleus was correlated with worse OS, which could serve as an independent biomarker for African-American triple-negative breast cancer." (PMID 35111813, 2021).
bladder cancer (8 papers, 2021 to 2025). "This study aimed to analyze KIFC1 expression and examine KIFC1 involvement in cisplatin resistance in bladder cancer (BC)." (PMID 34768355, 2021). "Furthermore, KIFC1 has been shown to enhance bladder cancer cell proliferation and induce epithelial-mesenchymal transformation via the Akt/GSK3β signaling pathway." (PMID 40379626, 2025). "KIFC1 was involved in bladder cancer proliferation, indicating that this involvement in proliferation may affect the sensitivity to cisplatin." (PMID 34768355, 2021). "As mentioned in the introduction, KIFC1 promotes bladder cancer cell proliferation in vitro." (PMID 34768355, 2021). "Previous studies revealed that kinesin family members [Kinesin family member C1 (KIFC1), Kinesin family member 5B (KIF5B), and Kinesin light chain 1 (KLC1)] play important roles in accelerating epithelial−mesenchymal plasticity in bladder cancer and breast tumors." (PMID 35811688, 2022).
breast tumors (8 papers, 2017 to 2024). "Primary breast tumors overexpress KIFC1 relative to matched normal breast tissue, while KIFC1 is expressed higher in TNBCs compared to non-TNBCs." (PMID 36139643, 2022). "Breast tumors display approximately five-fold higher KIFC1 expression compared to corresponding normal tissue, and KIFC1 is specifically upregulated in estrogen receptor-negative breast tumors and TNBC." (PMID 34945833, 2021). "Nuclear KIFC1 levels increase with increasing neoplastic progression and breast tumor aggressiveness." (PMID 34945833, 2021). "Further investigation into a potential racial disparity in KIFC1 levels in premalignant and pre-invasive samples may suggest a possible explanation for why individuals of African descent are more likely to develop breast tumors at a younger age and acquire aggressive tumor molecular subtypes." (PMID 34945833, 2021). "The results showed that KIFC1 expression was positively correlated with human breast tumor recurrence, but not with age." (PMID 33397932, 2021).
non-small cell lung carcinoma (6 papers, 2018 to 2025). A group of at least three distinct histological types of lung cancer, including non-small cell squamous cell carcinoma, adenocarcinoma, and large cell carcinoma. "Regarding aggressiveness, studies have suggested that KIFC1 expression is associated with brain metastasis in primary non-small cell lung cancer." (PMID 31340839, 2019). "Overexpression of KIFC1 promotes cell proliferation in non-small cell lung cancer." (PMID 31296617, 2019).
ovarian carcinoma (6 papers, 2014 to 2025). A malignant neoplasm originating from the surface ovarian epithelium. "Having established a significant correlation between KIFC1 expression and tumor differentiation, we next wanted to determine if there is any association between KIFC1 gene expression and clinical outcomes (overall survival (OS)) for ovarian cancer patients." (PMID 26992853, 2016). "Work is underway in our laboratory to pin point molecular mechanism to explain the association of KIFC1 and CA with ovarian cancer aggressiveness and poor patient outcomes." (PMID 26992853, 2016). "A centrosome clustering molecule, KIFC1, is indispensable for the viability of extra centrosome-bearing cancer cells, and may underlie progression of ovarian cancers." (PMID 25028599, 2014). "while in ovarian cancer, it interacts with kinesin family member C1 (KICF1) to boost the development, migration, and epithelial-mesenchymal switch of ovarian cancer." (PMID 38702677, 2024). "In the present study we have validated those findings by immunostaining ovarian cancer tissue samples for KIFC1." (PMID 26992853, 2016). "To further understand and validate results of our previous study, we herein evaluated KIFC1 expression in clinical samples of ovarian cancer by utilizing immunohistochemical staining." (PMID 26992853, 2016). "Given that ovarian cancers robustly display amplified centrosomes, we examined the overexpression of KIFC1 in human ovarian tumors." (PMID 26992853, 2016). "Using independent gene expression datasets, we identified that KIFC1 gene in ovarian cancer is expressed at least 2-fold (logarithm to base 2 scale) higher than in normal ovaries." (PMID 25028599, 2014). "To this end, we examined the expression of KIFC1, a known centrosome clustering molecule, and evaluated its prognostic power in ovarian cancer." (PMID 25028599, 2014). "We found KIFC1 levels to be significantly higher in ovarian cancer compared to normal ovarian epithelia." (PMID 25028599, 2014). "The overall survival was also lower in patients with high KIFC1 expression, implying its value as a prognostic biomarker in ovarian cancer." (PMID 25028599, 2014). "We first examined whether KIFC1 is upregulated in human ovarian cancers by analyzing KIFC1 overexpression in EOC clinical samples." (PMID 26992853, 2016). "Having identified a high degree of centrosomal clustering in ovarian cancers, we reasoned that these cells may rely heavily on KIFC1, a centrosome clustering molecule." (PMID 25028599, 2014). "Given our finding that KIFC1 expression increases with grade, we were next interested in determining whether it is expressed at higher levels in metastatic versus primary ovarian carcinomas." (PMID 25028599, 2014). "Our data compellingly underscores that KIFC1 can be a prognostic biomarker in ovarian cancers." (PMID 25028599, 2014). "A fold change for the means of Mas5.0 normalized intensity values in ovarian cancer (n = 1090) over normal ovarian samples (n = 38) revealed an approximately two fold difference, with an average KIFC1 expression value of ~5.86 for normal tissue and ~7.72 for tumors (p < 0.001)." (PMID 25028599, 2014). "Thus, increased KIFC1 expression correlated with poor overall survival in ovarian cancer patients." (PMID 25028599, 2014). "Our data underscore KIFC1 as a putative biomarker that predicts worse prognosis, poor overall survival and may serve as a potential marker of onset of metastatic dissemination in ovarian cancer patients." (PMID 25028599, 2014). "High expression of KIFC1 in ovarian cancer promotes proliferation, migration, and epithelial-mesenchymal transition (EMT) in ovarian cancer cells." (PMID 40612867, 2025). "We found that in clinical epithelial ovarian cancer (EOC) samples, an expression level of KIFC1 was significantly higher when compared to normal tissues." (PMID 26992853, 2016).
liver cancer (5 papers, 2021 to 2025). An epithelial or non-epithelial malignant neoplasm that arises from the liver. "In liver cancer, KIFC1 activates the gankyrin/AKT/TWIST1 pathway, promoting epithelial-stromal transformation and metastasis." (PMID 40379626, 2025). "In this study, we used UALCAN to analyze the promoter methylation of the KIFC1 gene in liver cancer and its relationship with clinical characteristics." (PMID 35111813, 2021). "Then, KIFC1 expression was further validated in liver cancer, and it indicated that patients with higher KIFC1 expression had worse prognosis." (PMID 35111813, 2021). "Previous studies have shown that KIFC1 can facilitate the occurrence of liver cancer." (PMID 35111813, 2021). "Moreover, the methylation level of the KIFC1 promoter in liver cancer is downregulated than normal and was negatively correlated with the individual cancer grade and stage of the LIHC patient." (PMID 35111813, 2021). "Moreover, the protein expression analysis from our clinical samples with IHC also indicated that KIFC1 was located and highly expressed near the nucleus of liver cancer cells, which was statistically different from that in normal liver tissues (8/36 vs. 1/36, chi-square test, p < 0.05)." (PMID 35111813, 2021).